CAVIN3 (caveolae associated protein 3)
Description:
Regulates the traffic and/or budding of caveolae. Plays a role in caveola formation in a tissue-specific manner. Required for the formation of caveolae in smooth muscle but not in the lung and heart endothelial cells. Regulates the equilibrium between cell surface-associated and cell surface-dissociated caveolae by promoting the rapid release of caveolae from the cell surface. Plays a role in the regulation of the circadian clock. Modulates the period length and phase of circadian gene expression and also regulates expression and interaction of the core clock components PER1/2 and CRY1/2 (By similarity).
Synonyms: hSRBC; PRKCDBP; SRBC; MGC20400; cavin-3
Tractability: Antibody: the Human Protein Atlas places it where antibodies can reach. PROTAC: UniProt records ubiquitination sites on it; ubiquitination databases record sites on it.
Gene: Protein-coding gene on chromosome 11 (6,318,946 to 6,320,546, reverse strand). Ensembl gene ENSG00000170955.
Subcellular location: Cytoplasm; Membrane, caveola; Cytoplasm, cytosol
Subcellular location (Human Protein Atlas): Plasma membrane
Gene Ontology:
Molecular function: protein binding; protein kinase C binding
Biological process: circadian regulation of gene expression
Cellular component: caveola; protein-containing complex; cytoplasm; cytosol
Genetic constraint (gnomAD): Loss-of-function variants: 12 observed, 6.76 expected, observed/expected ratio (o/e) 1.78, 90% interval 1.05 to 1.96. That is too few expected variants to judge how well the gene tolerates losing a copy. Missense variants: 336 observed, 238.91 expected, observed/expected ratio (o/e) 1.41, 90% interval 1.29 to 1.54. Synonymous variants: 164 observed, 110.86 expected, observed/expected ratio (o/e) 1.48, 90% interval 1.3 to 1.68.
Homologues: Orthologues: chimpanzee CAVIN3 (99% identical), macaque CAVIN3 (95% identical), pig CAVIN3 (90% identical), dog CAVIN3 (85% identical), guinea pig CAVIN3 (84% identical), rat Cavin3 (82% identical), mouse Cavin3 (81% identical), rabbit CAVIN3 (79% identical), zebrafish cavin2b (36% identical), tropical clawed frog cavin2 (31% identical), zebrafish cavin2a (30% identical). Paralogues in human: CAVIN2 (40% identical), CAVIN1 (27% identical), CAVIN4 (24% identical).
Diseases named in the same sentence as CAVIN3 in open-access papers:
CAVIN3 is named in the same sentence as 39 diseases in open-access papers, as found by Europe PMC text mining. Sharing a sentence is not in itself a finding about the gene and the disease. The quoted sentences say what the papers report.
breast carcinoma (16 papers, 2010 to 2024). "This is in accordance with the association study.Combination of the DAPK1 and CAVIN3 gene promotermethylations showed better results in the diagnosis of breast cancer." (PMID 34455714, 2021). "Methylation of the CAVIN3 was reported in lung and breast cancers where CAVIN3 was suggested as a tumor suppressor protein." (PMID 39162297, 2024). "Although some studies have shown that Cavin-3 plays a role in cancer inhibition in breast cancer, the specific molecular mechanism is not fully understood." (PMID 37828916, 2023). "Cavin-3 plays an anticancer role in breast cancer, but its specific mechanism of action is still unclear." (PMID 37828916, 2023). "Results elucidated that expression levels of CAV1, CAV2, CAVIN1, CAVIN2, and CAVIN3 were significantly lower in breast cancer tissues than in normal samples, while the expression level of CAVIN2 was correlated with advanced tumor stage." (PMID 34513683, 2021). "The results elucidated that the transcriptional levels of CAV1, CAV2, CAVIN1, CAVIN2, and CAVIN3 were significantly lower in breast cancer tissues than in normal samples." (PMID 34513683, 2021). "According to the genomic sequencing results from several investigated database, caveolae-related proteins all exhibited downregulation in breast cancer tissues except for CAVIN3." (PMID 34513683, 2021). "With respect to ROC analysis, thepromoter methylation of the CAVIN3 gene is able to be used, as a possiblediagnostic biomarker in breast cancer." (PMID 34455714, 2021). "Cavin-1 and Cavin-3 were down-regulated in breast cancer with a low progression-free survival rate." (PMID 35722492, 2022). "Cavin-3 is highly expressed in normal breast and lung epithelial cells, while it is absent in breast cancer, lung cancer and gastric cancer, which may be related to its promoter methylation, suggesting that Cavin-3 may play an anticancer role in breast cancer." (PMID 37828916, 2023).
lung carcinoma (10 papers, 2012 to 2024). "Lung cancers are not commonly detected until late in disease progression and loss of cavin-3 may facilitate stage progression to metastatic disease." (PMID 24069528, 2013). "They demonstrate that introducing cavin-3 into a lung carcinoma cell line in which cavin-3 is absent, leads to enhanced ERK activation and a reduction in both Akt signalling and aerobic glycolysis." (PMID 24069530, 2013).
colorectal cancer (7 papers, 2012 to 2023). A primary or metastatic malignant neoplasm that affects the colon or rectum. "Cavin3 inactivation was shown to be associated with the acquisition of chemoresistance to oxaliplatin in colorectal cancers." (PMID 33101009, 2020). "Cancers that commonly elicit cachexia include lung, breast, and colorectal cancers and these cancers frequently lack cavin-3 expression." (PMID 24069528, 2013). "A potential clue as to the role of cavin-3 in cancer comes from the observation that 35–55% of glial, lung, gastric, ovarian, breast, and colorectal cancers show hypermethylation in their cavin-3 promoters." (PMID 24069528, 2013).
breast tumors (3 papers, 2020 to 2024). "Low expression of CAVIN3 was related to hypermethylation of CAVIN3 in breast tumors." (PMID 39162297, 2024). "Cavin3 mRNA levels were further analyzed in 17 paired fresh-frozen breast tumor and tumor-adjacent tissues collected in SYSUCC, which showed the relative Cavin3 mRNA leves to β-actin were significantly lower in 14 out of 17 pairs of BC tissues compared with normal control, P=0.0047." (PMID 33101009, 2020).
non-small cell lung carcinoma (3 papers, 2013 to 2022). A group of at least three distinct histological types of lung cancer, including non-small cell squamous cell carcinoma, adenocarcinoma, and large cell carcinoma. "Strong selection pressure for loss of cavin-3 in cancer cells is suggested by the observation that while 41% of primary non-small cell lung carcinomas show methylation of their cavin-3 promoters, 81% of these carcinomas (N = 93) lack detectable cavin-3 expression by immunohistochemistry." (PMID 24069528, 2013). "Glucose consumption and lactate production reached rates that were equivalent to those observed in H1299 cells, a non-small cell lung carcinoma cell line that lacks cavin-3 expression." (PMID 24069528, 2013). "H1299 cells are a line of non-small cell lung carcinoma cells that lacked detectable cavin-3, but exhibited levels of cavin-1, caveolin-1, myosin-1c and actin that were similar to the endogenous levels of SV589 fibroblasts." (PMID 24069528, 2013).
lipodystrophy (2 papers, 2013 to 2014). A congenital or acquired disorder characterized by abnormal loss or redistribution of the adipose tissue in the body. "Lipodystrophy is frequently associated with hepatic steatosis and areas of steatosis were observed in livers of Cavin-3 KO animals." (PMID 24069528, 2013). "Cavin-3 KO mice did have shorter lifespan than control animals and the principal cause of death was cachexia as exemplified by a 40% reduction in body weight and severe lipodystrophy." (PMID 24069528, 2013). "The most apparent defect in Cavin-3 KO animals is cachexia as evidenced by a 40% reduction in weight and severe lipodystrophy." (PMID 24069528, 2013). "A cavin-3 knockout study was recently published, which reported that the null mice at 2 years of age had a 40% reduction on their body weight and severe lipodystrophy, and that knockdown of cavin-3 expression using siRNAs in fibroblasts caused loss of caveolae." (PMID 25036884, 2014). "Lipodystrophies have also been noted in humans and animals lacking either cavin-1 or caveolin-1 and the association of cavin-3 with cavin-1 and caveolin-1 combined with the dependence of cavin-3 protein on cavin-1 and caveolin-1 suggests that these lipodystrophies are caused by a common mechanism." (PMID 24069528, 2013). "Loss of cavin-3 linkage components may cause lipodystrophy through selective death in adipocytes; however, lipid mobilizing factors are elevated in the circulation of Cavin-3 KO animals (data not shown), suggesting that lipolysis is responsible for the loss of triglyceride stores." (PMID 24069528, 2013).
lung adenocarcinoma (2 papers, 2023). A carcinoma that arises from the lung and is characterized by the presence of malignant glandular epithelial cells. "However, CAVIN3 was found to be lower expressed in lung adenocarcinoma in Selamat Lung Statistics." (PMID 37497407, 2023).
age-related macular degeneration (1 paper, 2025). Age-related loss of vision in the central portion of the retina (macula), secondary to retinal degeneration. "Elevated CAVIN3 expression was observed in the ECs of retinal pigment epithelium/choroid complexes from patients with neovascular age-related macular degeneration and fibrovascular membranes from patients with proliferative diabetic retinopathy." (PMID 40337864, 2025).
aortic aneurysm (1 paper, 2015). A ruptured aneurysm located in the wall of the proximal portion of the descending aorta proceeding from the arch of the aorta. "We also examined caveolin-1 and cavin-3 staining in angiotensin II-induced aortic aneurysms in mice (the cavin-1 antibody was not ideal for staining of mouse tissues)." (PMID 26244347, 2015).
choroidal neovascularization (1 paper, 2025). An eye disorder described by the growth of new blood vessels that originate from the choroid through a break in the Bruch membrane into the sub–retinal pigment epithelium (sub-RPE) or subretinal space. "Additionally, upregulated Cavin3 expression was detected in laser-induced choroidal neovascularization (CNV) and oxygen-induced retinopathy (OIR) mouse models." (PMID 40337864, 2025). "Additionally, the upregulation of Cavin3 in ECs was observed in oxygen-induced retinopathy (OIR) and choroidal neovascularization (CNV) mouse models." (PMID 40337864, 2025).
invasive ductal carcinoma (1 paper, 2021). "The present study was designed to investigate promoter methylation status ofDAPK1 and CAVIN3 genes in plasma circulating free DNA (cfDNA) samples in Iranian invasive ductal carcinoma (IDC)patients." (PMID 34455714, 2021).
leukemia (1 paper, 2022). A malignant (clonal) hematologic disorder, involving hematopoietic stem cells and characterized by the presence of primitive or atypical myeloid or lymphoid cells in the bone marrow and the blood. "Finally, we investigated the prognostic value of CAVIN1, CAVIN2, CAVIN3, and CAVIN4 in leukemia using the R programming language to assess data from LinkedOmics." (PMID 35722492, 2022). "We then used the GEPIA and BloodSpot database to validate the unexpected result and found that high CAVIN2 expression was significantly associated with poorer OS in leukemia (p is 0.037 and 0.022 individually), but the trend was not significant for CAVIN1, CAVIN3 and CAVIN4." (PMID 35722492, 2022).
lymphoblastic leukemia (1 paper, 2022). "CAVIN3 can be either overexpressed or underexpressed in myeloid leukemias and lymphoblastic leukemia." (PMID 35722492, 2022).
lymphocytic leukemia (1 paper, 2022). "The results show that the transcription of CAVIN1, CAVIN2 and CAVIN3 were significantly lower than in normal samples from healthy donors, and the expression of CAVIN1 in myeloid leukemia is significantly higher than that in lymphocytic leukemia (p < 0.05)." (PMID 35722492, 2022).
Obesity (1 paper, 2020). Accumulation of substantial excess body fat. "The Cavin-3-dependent shedding mechanism appears to be an important process in adipocyte maturation, providing a potential therapeutic target for obesity-related disorders." (PMID 32679831, 2020). "Based on these findings, Cavin-3 might be used as an early marker of adipocyte differentiation, or further, a regulatory target for obesity-related disorders." (PMID 32679831, 2020).
tumor (22 papers, 2009 to 2026). "In humans, cavin-3 is encoded in the 11p15.5 tumor suppressor locus and loss of cavin-3 expression is common in many epithelial and glial derived cancers." (PMID 24069528, 2013). "CAVIN3 overexpression leads to cell cycle arrest, apoptosis, suppression of colony formation in vitro and inhibition of tumor growth in vivo in CRC models." (PMID 35747247, 2022). "CAVIN3 expression is commonly lost or decreased in CRC by aberrant CpG hypermethylation and loss of function is linked to tumor progression and poor prognosis." (PMID 35747247, 2022). "Several studies have emphasized the epigenetic modification of cavin-3 can contribute to the pathogenesis of cancer, indicating it as a tumor suppressor candidate." (PMID 34513683, 2021). "Cavin3, in turn, is considered a dynamic regulator of caveolae turnover and signal integration, linking caveolar function to cell signaling, DNA damage responses, and tumor suppression." (PMID 41668064, 2026). "Cavin3 inactivation may contribute to tumor progression by reducing cellular sensitivity to stressors as shown here as well as in previous published studies contributing to overall cell survival." (PMID 34142659, 2021). "Loss of cavin-3 protein has been reported in epithelial and glial-derived cancers, indicating that cavin-3 may be a tumour suppressor." (PMID 24069530, 2013). "Notably, CAVIN3 (Caveolae Associated Protein 3), identified here as predictive for PFS, is known to be downregulated in several cancer cell lines by genetic or epigenetic alteration and is considered a putative tumor suppressor." (PMID 35747247, 2022). "While cavin-3 knock-out mice do not generate tumours spontaneously, the loss of cavin-3 could contribute to metabolic changes that promote tumour growth." (PMID 24069530, 2013). "By contrast, module 2 and 3, which were only downregulated in EGF-stimulated SHP2WT cells, contained several tumor suppressors, such as NRG1, MAP3K1, CAVIN3, EPHA3/7, CTNNA1/3, and NOTCH3." (PMID 40631144, 2025). "Here patients with higher predicted CAVIN3 levels had shorter PFS, an apparent discrepancy possibly explained by the differences between normal transverse colon tissue and tumor tissue." (PMID 35747247, 2022). "The ability of cavin-3 to influence cell signaling, proliferation, metabolism, and apoptosis provides explanations for how cavin-3 functions as a tumor suppressor; however, Cavin-3 KO animals do not show substantial increases in spontaneous cancers." (PMID 24069528, 2013). "A protein that is concentrated in caveolae, cavin-3, suppresses tumor formation and is commonly absent from cancer cells." (PMID 24069528, 2013).
cancer (17 papers, 2011 to 2024). A tumor composed of atypical neoplastic, often pleomorphic cells that invade other tissues. "While deletion of the cavin-3 gene in mice is not sufficient to cause spontaneous cancer, animals that are deficient in cavin-3 die prematurely of cachexia, a tissue wasting sequela experienced by nearly half of all cancer patients." (PMID 24069528, 2013). "Consistent with this conclusion, loss of cavin-3 expression is more prevalent in late-stage/high-grade cancers than in early-stage/low-grade cancers." (PMID 24069528, 2013). "Loss of cavin-3 is common in cancer cells and many cancer cells show elevated Akt/mTORC1 signaling, aerobic glycolysis and resistance to apoptosis." (PMID 24069528, 2013). "Because loss of cavin-3 is associated with cancer in multiple tissues and cancer is associated with elevated mitogenic signaling, we hypothesized that loss of cavin-3 might augment signaling in response to growth factors." (PMID 24069528, 2013). "To test whether loss of the cavin-3 linkage is necessary for the altered cell signaling, metabolism and apoptosis phenotypes of cancer cells we tested whether reconstitution of the cavin-3 linkage was sufficient to normalize ERK/Akt signaling, cell metabolism and apoptosis." (PMID 24069528, 2013). "Among 261 AA‐specific methylated genes, several genes were investigated for their potential roles in various human cancers, such as CAVIN3." (PMID 39162297, 2024). "In the majority of human cancers, Cavin-1 is downregulated along with Cavin-2, Cavin-3 and Cavin-4 compared in cancer tissues vs. control tissues." (PMID 35722492, 2022). "Cavin-3 suppresses tumorigenic properties, interacts with the DNA damage repair pathway, regulates cancer cell invasion or metastasis and induces drug resistance by decreasing cell sensitivity to oxaliplatin." (PMID 35722492, 2022). "Our results suggest that Cavin3 and PP1α play opposite roles in the DNA damage response that is correlated with their protein expression in a number of cancers." (PMID 31332168, 2019). "To facilitate this reconstitution, we looked for a cancer cell line that lacks cavin-3, but expresses normal levels of all other linkage components." (PMID 24069528, 2013). "Trophoblast invasion shares many features with cancer cell metastasis and the degree of methylation in the cavin-3 promoter correlates with both trophoblast invasion potential and cancer metastasis." (PMID 24069528, 2013). "The absence or downregulation of Cavin-3 with promoter hypermethylation was found in various types of human cancer, especially at late stages of cancer, which could predict a low progression-free survival rate." (PMID 35722492, 2022). "Some of them have been reported as biomarkers in other types of cancers, such as GSTK1, IDH2, CAVIN3, HMGCS2, and ACOX1." (PMID 34557266, 2021). "Thus, the absence of cavin-3 in tumors may predispose patients to the development of cancer-associated cachexia, a condition that is the immediate cause of death for more than 20% of all cancer patients." (PMID 24069528, 2013). "Cavin-3 expression is also absent in many cancer cell lines and ectopic expression of cavin-3 in these cells is sufficient to suppress their tumorigenesis in athymic mice." (PMID 24069528, 2013). "During the course of these experiments, we determined that A431 cells (similar to several other commonly cancer cell lines such as HeLa cells) do not express Cavin2 but have significant expression of the universal components of caveolae, Cavin1, CAV1, and Cavin3." (PMID 31332168, 2019).
infection (1 paper, 2020). The state of being infected such as from the introduction of a foreign agent such as serum, vaccine, antigenic substance or organism. "Unlike wild type (wt) hPIV-2 infection, infection of rPIV-2/VW178H/W182E/W192A did not affect the rate of Cavin3 degradation." (PMID 32425917, 2020).
retinopathy (1 paper, 2025). "We first utilized the OIR mouse model to assess Cavin3 expression in retinopathy." (PMID 40337864, 2025).
CAVIN3 also shares sentences with these, for which no sentence is quoted: ovarian carcinoma (5 papers); neuroblastoma (4); gastric cancer (3); glioblastoma (2); anemia (1); aneurysm (1); brain cancer (1); Cachexia (1); colorectal tumors (1); glaucoma (1); Hepatic steatosis (1); invasive breast carcinoma (1); kidney disease (1); metabolic syndrome (1); metastatic disease (1); myeloid leukemia (1); proliferative diabetic retinopathy (1); renal tumours (1); steatosis (1); triple-negative breast carcinoma (1).